BAX (BCL2 associated X, apoptosis regulator)
Diseases named in the same sentence as BAX in open-access papers (continued):
Sharing a sentence is not in itself a finding about the gene and the disease.
infertile (8 papers, 2019 to 2025). "BAX deficient male mice have been shown to display increased apoptosis and infertility." (PMID 32456687, 2020). "Studies confirmed that infertile men showed a significant BAX increase and BCL2 decrease in seminal fluid at both mRNA and protein levels; moreover, the mature SPZ from infertile patients with increased ROS levels had significantly higher levels of apoptosis than mature SPZ from the control group." (PMID 40710375, 2025). "Also, the BAX/BCL-2 ratio of sperm in infertile men increased significantly compared to fertile men." (PMID 39205917, 2024). "Accordingly, an increase in the proportion of spermatozoa with fragmented DNA correlated with an elevated BAX/Bcl-2 ratio in semen obtained following longer ejaculatory abstinence with more uropathogenic bacteria, which has also been reported in infertile men suffering from urogenital infections." (PMID 36834909, 2023). "Prevention of apoptosis is also one of the mechanisms through which LC might have demonstrated anti-infertility effect against toxicants through modulation of proapoptotic and antiapoptotic genes, such as Bcl-2, BAX, and Caspase-3." (PMID 35814917, 2022). "BAX, LMNA, and WFS1 were associated with an infertility-related condition in DisGeNET database." (PMID 31694346, 2019). "Also, the mechanism of control over the rate of gene transcription or transcriptional regulation is altered in genes involved in chronic endometritis and the inflammatory response (IL-11, CCL4), growth factors (IGFBP1), and apoptotic proteins (BCL2, BAX, CASP8) in infertile patients." (PMID 33329514, 2020).
ischemia (8 papers, 2018 to 2025). A hypoperfusion of the BLOOD through an organ or tissue caused by a PATHOLOGIC CONSTRICTION or obstruction of its BLOOD VESSELS, or an absence of BLOOD CIRCULATION. "It has been demonstrated that OPA1-mediated downregulation of BAX can alleviate the loss of RGCs caused by ischemia." (PMID 36552630, 2022). "It was also reported that berberine has antiapoptotic effects against ischemia by reducing caspase-3 and increasing the Bcl-2/BAX ratio." (PMID 40235540, 2025). "Similarly, the apoptosis gene marker BAX exhibited a significant upregulation in experimental subgroup 2 compared to both the control and the ischemia group, while the anti-apoptotic BCL2 gene expression remained unchanged." (PMID 40009267, 2025). "Furthermore, it is also reported that the increases in the proportion of Bcl-2 to BAX can prevent myocardial apoptosis progress induced by ischemia and reperfusion." (PMID 33013403, 2020).
Cerebral ischemia (7 papers, 2016 to 2026). Restriction of arterial blood supply to the brain associated with insufficient oxygenation to support the metabolic requirements of the tissue. "A few early studies suggested that upregulation of BAX proteins in neuronal cells is a risk factor for cerebral ischemia." (PMID 35269511, 2022). "In the mouse transient middle cerebral artery occlusion (tMCAO) model, cerebral ischemia causes the MOAP1/BAX association, activating the MOAP1-dependent apoptosis cascade." (PMID 35269511, 2022). "BAX ablation might be a feasible direction to control cerebral ischemia, which makes MOAP1 critical in cerebral ischemia since it can regulate BAX and BCL2 in neurons." (PMID 35269511, 2022). "As BID is acting upstream of BAX in cell death signaling, these results indicate that other upstream, proapoptotic BH3-domain containing BCL-2 family proteins (“BH3-only proteins”) such as BIM and PUMA may play a more predominant role in BAX activation after cerebral ischemia." (PMID 26869884, 2016).
colitis (7 papers, 2021 to 2024). Inflammation of the colon. "At the same time, STAT3 knockout also reduced the differences in the expression of IL-6, TNF-α, and IL-1β, as well as ZO-1, occludin, BCL-2, and BAX in the colons of mice with colitis induced by different diets." (PMID 38233383, 2024). "In spite of this, SM934 regulated the balanced Bcl-2 and BAX, and cleaved caspase-9 and cleaved caspase-3 in colitis, and also downregulated the cleaved caspase-3 in TNF-α-induced IEC apoptosis in vitro." (PMID 36120344, 2022). "The RT-qPCR results showed that ghrelin reduced the mRNA expression of GPR78, CHOP, and BAX and increased the mRNA expression of Bcl-2 in a dose-dependent manner in mice colitis models, and such an effect of ghrelin could be reversed by [D-lys3]-GHRP-6." (PMID 33776781, 2021). "On the contrary, Alhagi/MSC significantly downregulated the expression of apoptosis and inflammasome-related proteins, such as NLRP3, BAX, and Caspase3 levels, and weakened the TUNEL positive signal in DSS-induced mouse colitis models, while it increased the PCNA expression levels." (PMID 38612465, 2024). "Serum was isolated from murine colitis models subjected to the JW treatment as well as healthy blank controls, and the JW serum did not influence BAX expression and the viability of NCM460 cells." (PMID 36091591, 2022). "In mouse colitis models, we found that ghrelin exhibited protective effects on colitis in a GHS-R1a-dependent manner, and the effects may be mediated by the UPR components, such as caspase-3, BAX, and Bcl-2, in intestine tissues." (PMID 33776781, 2021).
colon adenocarcinoma (7 papers, 2012 to 2024). "Gene expression profiling interactive analysis of BAX in colon adenocarcinoma has revealed a significantly higher expression of BAX compared to normal tissue." (PMID 39108882, 2024). "H2O2-mediated oxPTM of BAX can induce protein disulfide dimerization and translocation to the OMM52; this was seen in human colon adenocarcinoma cells upon Cys62 modification of BAX by H2O253." (PMID 33431811, 2021). "Moreover, the cytotoxic and pro-apoptotic effects of Bacillus coagulans on COLO205 colon adenocarcinoma cell line was also attributed to increased BAX/Bcl-2 ratio, increased caspase-3 levels and PARP cleavage." (PMID 38258008, 2024). "The induction of apoptosis by Epo and LFM-A-13 in the cells was confirmed by phosphatidylserine externalization, loss of mitochondrial membrane potential, and modulation of the expression of apoptotic protein BAX and antiapoptotic protein BCL-2 in colon adenocarcinoma cells." (PMID 29690619, 2018).
endometrial cancer (7 papers, 2013 to 2024). Primary or metastatic malignant neoplasm involving the endometrium (mucous membrane that lines the endometrial cavity). "The study also revealed that the expression of miR-29b is associated with the increased sensitivity of endometrial cancer cells to cisplatin and the cisplatin-induced enhancement of apoptosis through the regulation of BAX and Bcl-2 expression." (PMID 39518001, 2024). "As shown in the endometrial cancer pathway (hsa05213), both BAX and BIRC5 are Astragalus membranaceus targets that can inhibit tumour proliferation." (PMID 34513331, 2021). "Common genetic variants in the BCL-2-family genes BCL2, BAD, BAX and BAK1 were comprehensively evaluated for associations with endometrial cancer risk." (PMID 23637776, 2013). "The study demonstrated a connection between miR-135a and the increased proliferation and invasion of the tumor process, as well as showing that this marker inhibits the apoptosis induced by cisplatin in endometrial cancer cells by regulating the expression of BAX and Bcl-2." (PMID 39518001, 2024). "We investigated whether genetic variants in the BCL-2-family genes BAD, BAX, BCL2 or BAK1 are associated with endometrial cancer risk." (PMID 23637776, 2013). "In human endometrial cancer cells, EGCG treatment resulted in the suppression of anti-apoptotic protein BCL-2, the upregulation of pro-apoptotic BAX, and the activation of caspase-3 and PARP." (PMID 37189618, 2023). "Ectopic expression of LRIG2 downregulated the pro-survival BCL-2 family members, including MCL-1, BCL-xL, BCL2A1, and BCL-2, whereas the pro-apoptotic BCL-2 family members, such as BAK, BAX, and BAD, were upregulated by LRIG2 in endometrial cancer cells." (PMID 29358688, 2018). "Especially, inhibition of LRIG2-induced cell death by ectopic expression of MCL-1 or by depletion of either BAK or BAX further support our conclusion that LRIG2 induces apoptosis in Hec-1A endometrial carcinoma cells by regulating the delicate equilibrium among the BCL-2 family of proteins." (PMID 29358688, 2018).
lung adenocarcinoma (7 papers, 2015 to 2025). A carcinoma that arises from the lung and is characterized by the presence of malignant glandular epithelial cells. "The results demonstrated that upregulation of PTPRCAP expression in lung adenocarcinoma A549 cells significantly inhibited the protein levels of Bcl-2 compared with the vector groups, but the expression level of BAX and Caspase-3 increased (P < 0.05, n = 3)." (PMID 41411247, 2025). "For hsa-miR-511-3p, it has been reported to be related to lung adenocarcinoma by triggering BAX and TRIB2." (PMID 31105742, 2019). "Moreover, knockdown of EphA7 in lung adenocarcinoma has been found to increase apoptosis through regulation of BAX, Bcl-2, and caspase-3." (PMID 35103233, 2022). "Campesterol induced cell apoptosis through the mitochondrial pathway; it decreases the expression of BCL-2 and BCL-xL and increased the expression of BAX, BAD, BAK, and activating caspase 3 and caspase 9 in human lung adenocarcinoma (A549) cells." (PMID 33802602, 2021). "This is likely because SFN does not bind to proteins such as BAX or BAD, which regulate apoptosis or senescence in lung adenocarcinoma (data not shown, personal communication)." (PMID 26223682, 2015).
preeclampsia (7 papers, 2018 to 2024). Preeclampsia is a hypertensive disorder of pregnancy that is characterized by new-onset hypertension with proteinuria presenting after 20 weeks of gestation, and depending on mild or severe forms may initially present with severe headache, visual disturbances, and hyperreflexia. "Preeclampsia has been associated with increased markers of apoptosis in trophoblasts/the placenta, and we also observed an increase in the pro-apoptotic BAX/BCL2 ration in pre-term preeclamptic placentae." (PMID 30455461, 2018). "It has been recently demonstrated that berberine hydrochloride could alleviate preeclampsia by regulating IL2/IL10 and BCL2/BAX expressions in preeclampsia rat models." (PMID 29765977, 2018). "FA could also improve placental apoptosis in NG-nitro-l-arginine methyl ester (L-NAME)-induced preeclampsia (PE) rat model through increasing BCL-2 expression and decreasing BAX expression." (PMID 39268468, 2024). "In placenta from term preeclampsia, we found a decrease in pro-apoptotic BAX and an increase in anti-apoptotic BCL2, as well as no change in CASP9, demonstrating active mitochondrial suppression of apoptotic signalling and suggesting that mitochondria promote cell survival in these placentae." (PMID 30455461, 2018).
rectal cancer (7 papers, 2002 to 2025). A primary or metastatic malignant neoplasm that affects the rectum. "In rectal MSI-H carcinomas of the test series, we detected mutations only in IGF2R and BAX genes, possible indicating that they are also target genes in the MSI pathway in rectal cancer." (PMID 20979647, 2010).
type 2 diabetes (7 papers, 2017 to 2025). "We found that the expression of apoptosis-related gene (BAX gene) was significantly downregulated in subjects with alcohol, tobacco habits and patients with type 2 diabetes and hypertension." (PMID 36523663, 2022). "Type 2 diabetes is associated with increased APOE, BAX, MMP1, NFKB1, PDGFB, SPP1, and TGFB2." (PMID 35153741, 2021). "The increase in IL-11 levels is associated with decreased BAX protein production in obese patients with and without type 2 diabetes." (PMID 33579000, 2021).
virus infection (7 papers, 2020 to 2026). "At the time of assessment (24 hpi), vMIA/vIBO double-deficient virus infection produced a hypo-inflammatory state, suggesting that unleashed BAX and BAK reduce the amplification of inflammatory signaling." (PMID 34578288, 2021). "Therefore, BAX dysfunction can lead to various pathological diseases, including tumors and immune disorders caused by insufficient apoptosis and cardiovascular diseases, neurodegenerative diseases, and viral infections caused by excessive apoptosis." (PMID 36555999, 2022). "It has been demonstrated that BAX translocation to the mitochondria in response to virus infection or alcohol uptake induces mitochondria-mediated apoptosis." (PMID 38459007, 2024). "Subsequently, we assessed the mRNA levels of apoptosis-related proteins caspase 3, BAX, and Bcl-xL before and after virus infection and found that the level of caspase 3 mRNA was increased in the group treated with DON compared with that in the control group." (PMID 37175500, 2023). "During viral infection, cytosolic IRF3 is induced to form a complex with BAX, which then translocates to the mitochondria leading to apoptosis." (PMID 38459007, 2024). "Elimination of TNFR1-dependent signaling along with BAX/BAK must be evaluated for impact on cellular viability and in vivo replication during double-mutant virus infection." (PMID 34578288, 2021). "The ability of Wt1-5 infection to induce the expression of caspases 3 and 8 and pro-apoptotic proteins BAX, Bcl2, and BID suggest that virus infection, at least at late stages of the viral life cycle, leads to apoptotic cell death." (PMID 32722005, 2020). "Mitochondrial outer membrane permeabilization (MOMP), mediated by BAX/BAK-dependent membrane depolarization and promoted by PGAM5-mediated Bax translocation, is prominently induced by severe oxidative stress, viral infection, and apoptosis-inducing drugs." (PMID 41601699, 2026).
Anxiety (6 papers, 2019 to 2025). Intense feelings of nervousness, tension, or panic often arise in response to interpersonal stresses. "For instance, transgenic mice in which adult neurogenesis was suppressed by the expression of the pro-apoptotic protein BAX in neural progenitor cells show increased anxiety-related behaviors." (PMID 39176381, 2024). "In summary, exercise can effectively promote hippocampal neurogenesis and inhibit hippocampal cell apoptosis through the Caspase3/BCL‐2/BAX pathway, and then contributes to the amelioration of anxiety behavior in menopausal mice." (PMID 37402694, 2023). "Anxiety behavior in mice has also been observed through the deletion of the proapoptotic BAX gene in murine neural progenitor cells." (PMID 36163151, 2022). "Therefore, JSO ameliorates anxiety-like behaviors by upregulating BDNF expression, suppressing hyperactivation of the PI3K/AKT/mTOR signaling pathway, and reducing the BAX/BCL-2 ratio, thereby enhancing neuronal survival and synaptic plasticity." (PMID 40509387, 2025).
atherosclerosis (6 papers, 2018 to 2025). A disease characterized by the build-up of fatty material and calcium deposition in the arterial wall resulting in partial or complete occlusion of the arterial lumen. "The expression level of Vimentin, N-cadherin, Snail1, ZEB1, PI3K, p-AKT, p-mTOR and BAX in atherosclerosis and chronic stress were higher than that in control group." (PMID 37642954, 2023).
diffuse large B-cell lymphoma (6 papers, 2016 to 2025). "BAX and NFKBIA were implicated in susceptibility to CG-806 in a whole-genome CRISPR-Cas9 library screen (in a diffuse large B-cell lymphoma cell line)." (PMID 35296646, 2022). "To further confirm BAX expression, we tested NKTL, Diffuse large B-cell lymphoma (DLBCL), and Peripheral T-cell lymphoma (PTCL) patient samples using immunohistochemical." (PMID 37160920, 2023).
esophageal cancer (6 papers, 2013 to 2026). A primary or metastatic malignant neoplasm involving the esophagus. "Previously, studies have shown that BAX also plays a critical role in the determination of tumor response to radiation therapy in esophageal carcinoma cells." (PMID 30419865, 2018). "However, the favorable prognostic role of BAX has already been shown in other head and neck malignancies, such as oral squamous cell carcinoma and esophageal cancer." (PMID 23777485, 2013). "Although apoptotic biomarkers were not assessed in our study, the downregulation of Bcl-2 and the increase of BAX Might explain the results of our research, which indicates that DPMSC-CM caused the death of esophageal cancer cells by increasing apoptotic markers." (PMID 41585335, 2026). "Similarly, OCT1 was discovered to be directly regulated by STAT3 to reduce the expression of caspase 9, BAX, and BAD via ERK and AKT activation to boost proliferation and inhibit apoptosis in esophageal cancer cells." (PMID 26433389, 2016).
esophageal squamous cell carcinoma (6 papers, 2013 to 2025). Esophageal squamous cell carcinoma (ESCC) is a type of esophageal carcinoma (EC) that can affect any part of the esophagus, but is usually located in the upper or middle third. "Furthermore, the BAX/BCL2 ratio was shown to predict response to neoadjuvant radiochemotherapy in patients with advanced squamous-cell esophageal cancer." (PMID 23777485, 2013). "Inhibition of PLK1 by BI2536 treatment in esophageal squamous cell carcinoma (ESCC) induced pyroptosis both in vitro and in vivo through the BAX/caspase-3/GSDME pathway and boosted the sensitivity to cisplatin." (PMID 35719948, 2022). "In esophageal squamous cell carcinoma (ESCC), BI2536, an inhibitor of polo-like kinase 1(PLK1), was found to activate caspase-3 and BAX in combination with cisplatin, resulting in GSDME disruption and increased DNA damage." (PMID 35359956, 2022).
Obesity (6 papers, 2022 to 2025). Accumulation of substantial excess body fat. "Furthermore, exercise training not only enhances muscle biosynthesis but also reduces markers of muscle degradation, such as Atrogin‐1 and MuRF‐1, and protects against early mitochondria‐mediated apoptotic signaling caused by obesity (BAX/Bcl‐2 ratio and caspase‐3 expression)." (PMID 38684378, 2024). "In obese Zucker-fa/fa rats, BCL-2 mRNA levels were lower than in control rats, and BAX mRNA increased with the development of obesity." (PMID 39596317, 2024). "Here, for the first time, we examined the association between obesity, relative sperm telomere length (STL) and autophagy-related mRNA levels such as Beclin1, AMPKa1, ULK1, BAX, and BCL2." (PMID 37226085, 2023). "With this in mind, our purpose was to examine the association between obesity, relative STL, mRNA expression of autophagy-related genes (Beclin1, AMPKa1, ULK1, BAX, and BCL2), values of semen parameters, sperm DNA integrity, chromatin maturation, apoptotic changes, and intracellular ROS levels." (PMID 37226085, 2023). "Here, for the first time, we evaluated changes in autophagy-related genes (AMPKa1, Beclin1, ULK1, BAX, and BCL2) mRNA expression in spermatozoa from patients with obesity." (PMID 37226085, 2023). "Additionally, understanding how the BCL2/BAX ratio influences adipose tissue and ASCs, respectively, function in aging horses could provide valuable insights into managing age-related diseases in equines, including obesity, metabolic syndrome, and insulin resistance." (PMID 40646808, 2025).